LPL (lipoprotein lipase)
Diseases named in the same sentence as LPL in open-access papers (continued):
Sharing a sentence is not in itself a finding about the gene and the disease.
breast carcinoma (continued). "LPL has also been demonstrated to support the development and survival of breast cancer cells." (PMID 38339301, 2024). "Furthermore, there was a noticeable decrease in lipoprotein lipase (LPL), a metabolic enzyme implicated in breast cancer proliferation and metastasis." (PMID 38203396, 2023). "In addition, a careful examination of the classes and individual species of lipid hydrolysis products generated by LPL from lipoproteins, and their roles in breast cancer progression, remain to be understood." (PMID 36652113, 2023). "However, research toward understanding the roles of LPL in breast cancer (and other cancers) is in its infancy." (PMID 36652113, 2023). "This hypothesis article introduces lipoprotein lipase (LPL), provides a meta‐analysis of LPL mRNA expression in breast cancer, and explores a possible role for LPL in breast cancer." (PMID 36652113, 2023). "Overall, we hypothesize that the lipid hydrolysis products that are generated from lipoproteins by LPL impact the breast cancer cell microenvironment, ultimately decreasing prognosis due to increased proliferation and metastasis." (PMID 36652113, 2023). "In addition to de novo synthesis, upregulation of lipid uptake by VLDL receptors and lipoprotein lipase (LPL) in breast cancer cells contributes to increased lipid uptake." (PMID 35008394, 2022). "However, the role of lipoprotein hydrolysis products generated by LPL on cytokine secretion in breast cancer remains to be investigated." (PMID 34404457, 2021). "In addition, knockdown of CD44 or intratumoral injection of tetrahydrolipostatin (LPL inhibitor) can inhibit breast cancer progression and angiogenesis." (PMID 34834495, 2021). "Thus, our objective was to determine if hydrolysis products generated by LPL from total lipoproteins can also promote pro-inflammatory cytokine secretion from breast cancer cells." (PMID 34404457, 2021). "Our study shows that products of lipid hydrolysis from total lipoproteins by LPL may promote breast cancer growth and progression by inducing a pro-tumorigenic cytokine secretion profile from tumor cells, independent of cell metabolic activity." (PMID 34404457, 2021). "Recent study reported that LPL promoted breast cancer cell growth and survival." (PMID 31740790, 2020). "This hypothesis article aims to introduce LPL, provide a meta‐analysis of LPL mRNA expression in breast cancer from data mined via the KMplot online analysis tool, and explore its possible role in breast cancer." (PMID 36652113, 2023). "Moreover, Pang-Kuo Lo and colleagues identified that women with basal-type triple-negative human breast cancer have a higher expression of endothelial lipase, a lipoprotein lipase belonging to the triglyceride lipase gene family, in comparison with other types of cancer." (PMID 35798767, 2022). "Indeed the aggressive “triple-negative” breast cancer cell lines express lipoprotein lipase (LPL), the key enzyme for extracellular lipolysis, and the transmembrane channel for exogenous free FA uptake (CD36), together with the classical lipogenic markers such as FASN." (PMID 26452259, 2015). "Subsequently, we further narrowed down the eight candidate genes (TRIM47, SPHK1, RGMA, ROPN1B, LARP6, ROPN1, NPM2 and LPL) that are shared in TNBC compared to ER+ and HER2+ breast cancer subtypes in cancer cells." (PMID 40635123, 2025). "PCK1, LPL, and SFRP2 play a role in breast cancer’s initial and developmental stages, and KRT6B is exclusively related to the developmental stages." (PMID 38791477, 2024). "A clinical investigation involving 24 breast cancer patients administered CLA orally at 7.5 g/day for 20 days revealed inhibition in the expression of fatty acid synthase (FASN) and lipoprotein lipase (LPL), indicating breast tumor growth suppression." (PMID 38592012, 2024). "Thus, an exploration into the role(s) LPL may play in various breast cancer subtypes is warranted." (PMID 36652113, 2023).
breast carcinoma (continued). "Lipids can be delivered to cells by lipoprotein lipase (LPL), an extracellular lipase that hydrolyzes triacylglycerols and phospholipids from lipoproteins, that is expressed by adipose tissue and some breast cancer cell lines." (PMID 34404457, 2021). "Perhaps the most intriguing finding from our study was that CL-TNBC, specifically, had much higher expression of CD36, LPL, PDGFRB, FABP4, and PDK4 compared to all other breast cancers, including basal-TNBC." (PMID 31942031, 2020). "We created a “fatty acid metabolism gene signature” consisting of CD36, LPL, PDK4, and FABP4 and checked each molecular subtype of breast cancer for upregulation or amplification of these genes." (PMID 31942031, 2020). "Conversely, lipoprotein lipase (LPL) and CD36 are frequently highly expressed in breast cancer tissue, and their overexpression in breast cancer cell lines activates a lipolytic pathway that enhances growth in culture." (PMID 27635066, 2016). "Thus, for the current study, our objective was to examine the cytokine expression profiles of breast cancer cells with differing ER/PR and HER2 receptor status, in response to total lipoprotein hydrolysis products generated by LPL." (PMID 34404457, 2021). "Although it was originally thought that breast cancer cells did not have access to circulating lipids due to lack of LPL, a more recent study confirmed that basal-like breast cancer cell lines express significant levels of LPL mRNA." (PMID 28412757, 2017). "Interestingly, the most detrimental subtype of breast cancer, triple‐negative breast cancer, has been shown to exploit exogenous lipid uptake in part through LPL." (PMID 36652113, 2023). "Despite consistent correlation in expression between CD36, LPL, PDK4, and FABP4 in all breast cancer subtypes (data not shown), the only subtype that displayed poorer survival was CL-TNBC (p = 0.0119; HR = 1.92)." (PMID 31942031, 2020). "We found that both LPL and LIPC were underexpressed in invasive ductal carcinomas (IDCs) and were not differentially expressed among distinct molecular breast cancer subtypes." (PMID 29350614, 2018).
Hypertension (29 papers, 2009 to 2025). The presence of chronic increased pressure in the systemic arterial system. "The LPL Ser447Ter polymorphism is the most intensively studied regarding its association with blood pressure (BP) and risk of hypertension." (PMID 37510094, 2023). "In contrast to HMGCR inhibitors, LPL targets were associated with reduced risks of cardiovascular events, T2D, hypertension, and NAFLD, indicating the promising roles of developing newer nonstatin therapies through the LPL pathway." (PMID 38127052, 2023). "LPL Ser447Ter is the most common polymorphism of LPL and has been assessed for its association with blood pressure and risk of hypertension." (PMID 36551995, 2022). "In the present investigation, we report a genetic association study on obese and hypertension using three candidate loci (ApoB, LPL and Leptin)." (PMID 19772655, 2009). "For instance, decreased APOA4, APOC1, and APOC3 expression would result in reduced lipid removal from the vascular wall and inhibition of lipoprotein lipase activity, potentially promoting lipid accumulation, which might be associated with hypertension." (PMID 34929167, 2022). "In other studies, a correlation between LPL Ser447Ter and hypertension was observed in subjects with phenotypic features of MetS." (PMID 37510094, 2023). "On the contrary, a positive relationship was observed between LPL Ser447Ter with hypertension in subjects displaying MetS features." (PMID 36551995, 2022). "Here, we presented the results showing that AngII, a potent inducer of hypertension, also regulates TG metabolism in adipocytes; the hormone suppressed LPL expression in VAT but, conversely, enhanced it in SAT." (PMID 26447765, 2015). "The results of previous studies have been contradictory, suggesting both positive and negative associations between LPL polymorphism and hypertension." (PMID 37510094, 2023). "The 2 variants with this pattern of association include (i) COBLL1:p.N497D which is associated with decreased TG levels and decreased risk of T2D in both HUNT and UK Biobank and of liver disease in HUNT and (ii) LPL:p.S474X which is associated with decreased risk of CAD, T2D, and hypertension." (PMID 33339817, 2020). "Based on their disease–gene associations, these biomarkers are involved in vascular inflammation (HO-1, LPL, PAPPA, ADAMTS13, ADM, PGF, and GDF-2), hypertension, and arterial disease (PAPPA, ADAMTS13, ADM, and PGF)." (PMID 35327515, 2022).
steatosis (24 papers, 2008 to 2025). Increased lipid within the cytoplasm of cells. "Results from this study may imply that GA could counteract the development of visceral obesity and improve dyslipidaemia via selective induction of tissue LPL expression and a positive shift in serum lipid parameters respectively, and retard the development of IR associated with tissue steatosis." (PMID 19638239, 2009). "The DOS improved liver tissue steatosis in the model rats, which in turn reduced the LPL content in the liver tissue." (PMID 32308702, 2020). "In LCKD-fed ob/ob mice, the generation of triglyceride-rich VLDL and maintained LPL activity promote the transport of triglycerides from the liver to extrahepatic tissues, ultimately leading to improvement of steatosis." (PMID 31815184, 2019). "A recent study shows that an up-regulation of LPL evoked an insulin resistant state in hepatocytes in mice and finally developed into hepatic steatosis." (PMID 23110339, 2012). "Elevated ANGPTL8 levels in earlier steatosis/steatohepatitis stages may exacerbate disease progression through inhibitory effects on the lipoprotein lipase activity." (PMID 40276549, 2025). "Increased LPL activity could enhance the ability of hepatocytes to capture circulating triglycerides, leading to steatosis typically being observed in these patients." (PMID 34977107, 2021). "On the basis of these evidences, the measurement of circulating FAS and LPL could be useful in the management of metabolic diseases, as steatosis." (PMID 23110339, 2012). "To our knowledge, we show for the first time, elevated levels of LPL activity in serum from patients with severe steatosis, suggesting that serum LPL activity measurement may add substantial information for the evaluation of liver impairment." (PMID 23110339, 2012). "In LCKD-fed wild-type mice, induction of hepatic VLDLR expression and decreased serum LPL activity inhibit the transport of triglycerides by VLDL from the liver to extrahepatic tissues, ultimately promoting steatosis." (PMID 31815184, 2019). "In the HC group (rats with steatosis induced by the fatty diet), genes such as ABCG1 and LPL were over-expressed." (PMID 30987167, 2019). "Higher interferon expression was shown to lead to suppression of lipoprotein lipase, which would result in decreased conversion of VLDL to LDL and subsequent higher steatosis." (PMID 24637774, 2014). "The subjects with steatosis showed circulating levels of FAS and LPL significantly higher than controls." (PMID 23110339, 2012). "Improved Lipid Metabolism: The upregulation of peroxisome proliferator-activated receptor alpha (PPARα) and lipoprotein lipase (LPL) expression enhances fatty acid oxidation and lipid clearance, while reduced fatty acid synthase (FAS) expression decreases lipogenesis and steatosis." (PMID 40136563, 2025). "LPL enables the liver to hydrolyze TG from chylomicrons and VLDL, not only helping to clear plasma lipids, but also leading to an increase in hepatic uptake of NEFA and, therefore, steatosis." (PMID 35739867, 2022). "The gene expression of LPL is higher in obese subjects with NAFLD than in subjects without NAFLD, suggesting that free fatty acids released by the lipolysis of circulating triglycerides also contribute to hepatocellular fatty acid accumulation and steatosis." (PMID 30987167, 2019). "Fatty acid synthase (FAS), a key enzyme in de novo lipogenesis, and Lipoprotein lipase (LPL), the rate-limiting enzyme for the hydrolysis of core triglycerides in chylomicrons and VLDL, have been detected at elevated levels in serum from patients with steatosis." (PMID 33918878, 2021).
steatosis (continued). "Still, abundant steatosis is not an immediate outcome of the highly increased expression level of PPARG, FABP4, CD36, and LPL in the liver of the severly obese minipigs." (PMID 32205840, 2020). "In the group of rats that were taking tomato juice (with and without steatosis), the genes involved in β-oxidation as well as the thrombospondin receptor (CD36) were positively regulated, and apolipoprotein B (APOB) and lipoprotein lipase (LPL) were negatively regulated." (PMID 31330977, 2019).
Hyperinsulinemia (21 papers, 2009 to 2025). An increased concentration of insulin in the blood. "The subsequent hyperinsulinemia inhibits hormone sensitive lipase and triggers the lipoprotein lipase causing additional glucose intolerance, hyperinsulinemia, hypertriglyceridemia and higher risk of insulin resistance in these tissues." (PMID 29940972, 2018). "It is involved in the processes of carbohydrate and lipid metabolism, leading to hyperinsulinemia, by altering the expression of insulin receptors, and increasing levels of fatty acids and glycerol, by inhibiting lipoprotein lipase and increasing lipolysis." (PMID 40717997, 2025). "Hyperinsulinemia, by decreasing lipoprotein lipase activity, leads to increase serum TGs levels, which is an independent cardiovascular risk factor." (PMID 35407635, 2022). "Hyperinsulinemia decreases expression of Lipoprotein Lipase (LPL), an enzyme responsible for lipolysis, in skeletal muscle, but increases LPL expression in adipose tissue." (PMID 26225266, 2015). "For example, it is well known that postprandial hyperinsulinemia promotes the storage of TG in adipose tissue by increasing LPL activity and that skeletal muscle LPL activity and TG storage are minimal." (PMID 25061524, 2014). "LPL activity was found positively correlated with hyperinsulinemia, thus contributing, with increased apo C-III and reduced apo CII, to lowered LPL activity." (PMID 19709414, 2009). "Peripheral hyperinsulinemia, a consequence of subcutaneous insulin delivery, may explain these findings by directly increasing lipoprotein lipase (LPL) activity." (PMID 40755902, 2025). "According to the in vitro studies, factors such as increased estradiol concentration or the combined effect of hyperglycemia and hyperinsulinemia may be responsible for the increase in LPL activity." (PMID 38542532, 2024). "In addition, several studies in animal models and humans suggest that hyperinsulinemia can over-stimulate the catecholamine pathway and that NE inhibits LPL in specific tissues." (PMID 31284400, 2019). "The question is whether exercise-mediated increases in skeletal muscle LPL activity are maintained in the presence of hyperinsulinemia as in the postabsorptive state or if exercise increases adipose tissue LPL activity." (PMID 25061524, 2014). "Hyperinsulinemia disturb the activation of LPL and involve accumulation of VLDL and LDL." (PMID 19709414, 2009). "Reduction of LPL activity in these patients was attributed to its increased essential inhibitor cofactor apo-CIII and diminished essential cofactor activator apo CII and hyperinsulinemia." (PMID 19709414, 2009).
hypothyroidism (20 papers, 2006 to 2025). Abnormally low levels of thyroid hormone. "Additionally, our study also provided suggestive evidence for the potential therapeutic use of ANGPTL3 inhibitors for both hypothyroidism and hyperthyroidism, while showing that LPL activation was related to increasing hyperthyroidism risk." (PMID 38425755, 2024). "Furthermore, the study suggests potential therapeutic implications of ANGPTL3 inhibition for both hypothyroidism and hyperthyroidism, alongside the observed risk increase in hyperthyroidism with LPL activation." (PMID 38425755, 2024). "In addition, genetic mimicry of LPL activation exhibited neutral effects on hypothyroidism risk in both datasets." (PMID 38425755, 2024). "Additionally, overt hypothyroidism is associated with a reduction in lipoprotein lipase (LPL) activity, which impairs the clearance of TG-rich lipoproteins." (PMID 35186143, 2022). "Furthermore, a decrease in activity of lipoprotein lipase which causes the clearance of TG-rich lipoproteins to decrease and TG level to increase was noted in hypothyroidism, and the raised HDL-C caused by decrease of hepatic lipase activity was also observed." (PMID 30927245, 2020). "Additionally, the activity of the lipoprotein lipase enzyme is reduced in hypothyroidism; therefore, hypothyroidism may be associated with higher triglyceride levels." (PMID 37773140, 2023). "The increase in serum TG level in hypothyroidism usually refers to the decrease in TG-rich lipoprotein clearance secondary to inhibition of lipoprotein lipase activity." (PMID 40672362, 2025). "Increased TG levels in hypothyroidism are attributed to normal or reduced activity of lipoprotein lipase in adipose tissue and decreased hepatic lipase activity." (PMID 37876378, 2023). "On the other hand, LPL activity has been found reduced in hypothyroidism and increased in hyperthyroid state." (PMID 29752428, 2019). "Hypothyroidism can also lead to increased serum triglyceride levels by decreasing hepatic lipoprotein lipase activity." (PMID 27143968, 2016). "Contrasting with the push for lipolysis, hyperthyroidism induces down regulation of adipose fatty acid synthase and lipoprotein lipase; most of these effects reversed in hypothyroidism." (PMID 16472384, 2006). "Studies in humans with hypothyroidism and elevated plasma TG have shown that the administration of T4 induced a reduction of plasma VLDL cholesterol and triglyceride, associated with an increased LPL activity." (PMID 29752428, 2019). "Moreover, a decrease in lipoprotein lipase (LPL) activity is found in overt hypothyroidism which decreases the catabolism of TG rich lipoproteins; therefore OH patients showed to have increased TG levels." (PMID 26064115, 2015).